S100A4 (S100 calcium binding protein A4)
Diseases named in the same sentence as S100A4 in open-access papers (continued):
Sharing a sentence is not in itself a finding about the gene and the disease.
proliferative diabetic retinopathy (2 papers, 2022 to 2025). Advanced retinopathy due to diabetes mellitus characterized by the formation of new vessels in the retina. "S100A4 is upregulated in proliferative diabetic retinopathy and is associated with angiogenesis and fibrosis markers." (PMID 40718484, 2025).
promyelocytic leukaemia (2 papers, 2002 to 2017). "Expression of S100A4 was found to be induced during macrophagic or granulocytic differentiation of human promyelocytic leukemia cells, which coincided with the cell motility, suggesting that S100A4 was involved in the regulation of leukemic cell motility." (PMID 29069865, 2017).
prostate adenocarcinoma (2 papers, 2019 to 2021). "In line with this survival data, it was also reported that S100A4 level was significantly higher in prostate adenocarcinoma compared with benign prostate hyperplasia." (PMID 33549040, 2021). "In addition, the effect of S100A4, ACKR3, and CDH1 expression on overall survival (OS) was assessed using the TCGA-prostate adenocarcinoma (PRAD) dataset." (PMID 31895690, 2019).
pterygium (2 papers, 2009 to 2021). A wedge-shaped fibrovascular lesion arising from the bulbar conjunctiva and extending to the cornea. "In both conjunctiva and pterygium, S100A4-positive cells were found in superficial and suprabasal layers." (PMID 19223989, 2009). "S100A4 expression was found in the superficial and suprabasal layers of both the normal conjunctival and pterygium epithelia." (PMID 19223989, 2009). "The differential localization of S100A4 and S100A6 demonstrated in our study raises the possibility of a stem cell defect in pterygium." (PMID 19223989, 2009). "S100A4, S100A6, S100A8, S100A9, and S100A11 gene transcripts were detected in conjunctiva and pterygium tissues." (PMID 19223989, 2009). "Western blot and RT–PCR confirmed the presence of S100A4, S100A6, S100A8, S100A9, and S100A11 in pterygium and conjunctiva tissue." (PMID 19223989, 2009). "Our investigation revealed that S100A4, S100A6, S100A8, S100A9, and S100A11 are expressed in both the normal and pterygium epithelia." (PMID 19223989, 2009). "Immunofluorescent staining detected the presence of S100A4, S100A6, S100A8, S100A9, and S100A11 in normal human conjunctival and pterygium epithelia." (PMID 19223989, 2009). "Similar to the protein expression, S100A4 and S100A11 did not demonstrate any significant difference in expression in either pterygium or conjunctival tissues." (PMID 19223989, 2009). "Protein levels of S100A4 and S100A11 in the pterygium tissue was not significantly different compared with the normal conjunctiva." (PMID 19223989, 2009).
rectal cancer (2 papers, 2016 to 2023). A primary or metastatic malignant neoplasm that affects the rectum. "In particular, S100A4 accurately predicted poor survival with high sensitivity and specificity for patients with CRC independently on cancer type, so S100A4 can be a universal unfavorable predictor in colon and rectal cancers." (PMID 36895491, 2023). "Thus, S100A4 expression was higher in rectal cancer patients having tumor stages I-II compared to patients with stage III (28,20 ± 22,29 vs 21,47 ± 19,29, p=0,046)." (PMID 36895491, 2023). "Finally, our results indicate that chemotherapy-based treatment can change the predictive direction of S100A4 for rectal cancer patients." (PMID 36895491, 2023). "Using digital quantification, we performed IHC analysis of S100A4, SPP1 and SPARC in human colon and rectal cancer tissue." (PMID 36895491, 2023). "We for the first time performed complex analysis of S100A4, SPP1 and SPARC mRNA levels in terms of survival rates in common CRC groups and in patients with colon and rectal cancer separately." (PMID 36895491, 2023). "The similar results were found for OS, DSS, DFS, and PFS in both patients with colon and rectal cancer, indicating that prognostic significance of S100A4 mRNA expression does not depend on cancer type." (PMID 36895491, 2023). "Using GSE190826 cohort we showed that pre-treatment S100A4 mRNA expression in rectal cancer patients who had not achieve pathological complete response (pCR) after CRT and suffered from the recurrence, was lower than in patients without progression (7,25 ± 0,81 vs. 6,64 ± 0,82, p=0,049)." (PMID 36895491, 2023).
renal carcinoma (2 papers, 2014 to 2020). A carcinoma arising from the epithelium of the renal parenchyma or the renal pelvis. "This role of S100A4 in human MM invasiveness is also consistent with the observation of a decreased survival probability for patients with renal cancer and high S100A4 expression." (PMID 32290283, 2020). "This is probably due, at least in part, to the decreased S100A4 expression, since it has been shown before that S100A4 promotes proliferation and migration in renal carcinoma cells." (PMID 25152734, 2014). "S100A4 is known to stimulate proliferation and metastasis in renal carcinoma cells." (PMID 25152734, 2014).
renal cell carcinoma (2 papers, 2014 to 2025). "Recent studies have shown that elevated S100A4 protein levels are positively correlated with various human tumors and are associated with poor prognosis in human gastric, colorectal, pancreatic, thyroid, breast, lung, prostate and renal cell cancer." (PMID 25310523, 2014). "Cells from renal cell carcinoma (RCC) tissue in the dataset GSE167573 showed tumorous samples to have multiple exonic regions in several genes, among them SPP1 or ‘ENSG00000118785’ with five exons, S100A4 with two exons and CXCL12 with five exons." (PMID 39857756, 2025).
renal failure (2 papers, 2017 to 2025). "This elevated S100A4 expression in Th17 cells further underscores the heightened inflammatory or pathogenic potential of the Th17 lineage within the renal insufficiency cohort." (PMID 40584830, 2025). "S100A4 has also shown prognostic value as a biomarker in immunoglobulin A nephropathy, with the number of S100A4-positive cells on biopsy found to predict renal failure and corticosteroid responsiveness." (PMID 29065913, 2017). "These patterns underscore a possible mechanism by which elevated S100A4 may bias T-helper differentiation away from a regulatory fate, potentially exacerbating allograft injury in patients with renal insufficiency." (PMID 40584830, 2025).
sarcoma (2 papers, 2023). A usually aggressive malignant neoplasm of the soft tissue or bone. "In sarcoma, the expression levels of ANXA1 were positively correlated with those of MMP9 (r=0.204, P=9.43e-04), COL1A2 (r=0.349, p=8.87e-09), S100A4 (r=0.574, P<0.001), VIM (r=0.48, P<0.001) and S100A11 (r=0.638, P<0.001)." (PMID 36988561, 2023).
Sepsis (2 papers, 2025 to 2026). Sepsis is defined as life-threatening organ dysfunction caused by a dysregulated host response to infection. "It has been reported that the shift from a Th1 to a Th2 cell profile contributes to sepsis-associated immune dysfunction, and effector-memory T cells (Tem) expressing the Igals3 and S100a4 genes." (PMID 40096073, 2025). "The S100A4/STAT3 axis promotes AEC‐II‐derived exosomal Rmrp expression and enhances the inhibitory effect of AEC‐II‐derived exosomes on the immune responses and glycolysis of AMs following sepsis." (PMID 41178622, 2026).
tendinopathies (2 papers, 2018 to 2022). "This evidence supports the suggestion that S100a4 acts as the upstream mediator of αSMA, even though S100a4 expression is lost during the transition from TDSCs to SCX+αSMA+ cells, with this increased expression of SCX+S100a4+ cells leading to fibrotic tendinopathies (Fig. 1iii)." (PMID 36056395, 2022).
thyroid tumor (2 papers, 2005 to 2012). A benign or malignant neoplasm affecting the thyroid gland. "Presently, little is known about the potential role of S100A4 in thyroid tumour invasion and metastasis." (PMID 16265347, 2005). "In the present study, we have shown increased S100A4 expression in thyroid tumour cells metastasised to regional lymph nodes or distant organs and at the tumour invasion front in matched primary thyroid tumour and their metastatic specimens." (PMID 16265347, 2005). "The results suggest that overexpression of S100A4 may play an important role in thyroid tumour invasion and metastasis." (PMID 16265347, 2005).
acute respiratory distress syndrome (1 paper, 2022). Progressive and life-threatening pulmonary distress in the absence of an underlying pulmonary condition, usually following major trauma or surgery. "This study shows a link between S100A4, the S100A8/A9 heterodimer, and S100A10 and LDH levels, suggesting these molecules contribute to acute lung injury and ARDS (acute respiratory distress syndrome)." (PMID 35892571, 2022).
airway hyperresponsiveness (1 paper, 2023). "After anti-S100A4 antibody administration, pathophysiological signs, including airway hyperresponsiveness and increased infiltration of inflammatory cells, were attenuated." (PMID 37873538, 2023). "We evaluated the effect of anti-S100A4 on airway hyperresponsiveness in response to acetylcholine chloride." (PMID 37873538, 2023). "However, anti‐S100A4 administration resulted in a marked reduction of lung resistance in OVA mice, suggesting that anti‐S100A4 inhibited airway hyperresponsiveness." (PMID 37873538, 2023).
allergic rhinitis (1 paper, 2022). Inflammation of the nasal mucous membranes caused by an IgE-mediated response to external allergens. "A recent study observed that S100A4 expression was increased in the serum of allergic rhinitis patients, and s100A4 gene knockout presented a protective effect against allergic inflammation in animal models, suggesting that S100A4 might be closely involved in airway inflammation." (PMID 36386522, 2022).
Aortic dissection (1 paper, 2024). Aortic dissection refers to a tear in the intimal layer of the aorta causing a separation between the intima and the medial layers of the aorta. "Further analysis demonstrated that S100A4 was significantly overexpressed in mice with aortic dissection." (PMID 38164183, 2024).
Autoimmunity (1 paper, 2015). The occurrence of an immune reaction against the organism's own cells or tissues. "Again, we did not observe any modification in the capacity of T cells to mediate autoimmunity that could have been caused by the lack of S100A4 expression and mice adoptively transferred with S100a4Gfp/Gfp CD4+ T cells developed EAE to the same extent as those receiving S100a4+/+ CD4+ T cells." (PMID 26734465, 2015). "Thus, the loss of S100A4 expression did not modify the capacity of T cells to migrate to target organs and mediate locally autoimmunity." (PMID 26734465, 2015). "Moreover, T cell memory response was normal in S100A4‐deficient mice and lack of S100a4 gene expression did not induce any defect in promoting the development of protective immunity or inflammatory reactions leading to autoimmunity." (PMID 26734465, 2015).
autonomous diseases (1 paper, 2021). "According to the context, S100A4 can elicit compounding effects, and should therefore be taken into consideration in strategies of intervention for multifactorial non-cell autonomous diseases as those represented by neurological disorders." (PMID 33918416, 2021).
bronchioalveolar carcinomas (1 paper, 2021). "Interestingly, S100A4 has some antitumorigenesis properties as 10% of S100a4−/− mice develop spontaneous tumors that are p54 positive, including bronchioalveolar carcinomas." (PMID 34239729, 2021).
choriocarcinoma (1 paper, 2020). An aggressive malignant tumor arising from trophoblastic cells. "Abnormal nuclear location of S100A4 can be viewed as a signal for tumor invasion, and downregulation of SUMOylation may help in choriocarcinoma therapy." (PMID 33273928, 2020). "Treatment of choriocarcinoma (CCA) cells with ginkgolic acid, a SUMOylation inhibitor, results in low levels of the nuclear S100A4 expression that inhibit CCA cell invasion and proliferation." (PMID 33273928, 2020).
chronic thromboembolic pulmonary hypertension (1 paper, 2022). Chronic thromboembolic pulmonary hypertension (CTEPH) is characterized by the persistence of thromboemboli in the form of organized tissue obstructing the pulmonary arteries. "We therefore quantified S100A4, EGF, and EGFR in patients suffering from chronic thromboembolic pulmonary hypertension (CTEPH) and idiopathic pulmonary arterial hypertension (iPAH)." (PMID 35053115, 2022).
congenital heart disease (1 paper, 2015). A heart disease that is present at birth. "Children with congenital heart disease show PH with pulmonary vascular lesions and an increase in S100A4 expression." (PMID 26483185, 2015).
cortical cataract (1 paper, 2021). A cataract (disease) that involves the lens cortex. "In this study, we demonstrate that S100A4 expression is robustly induced in differentiating fiber cells of the ocular lens and that S100A4(−/−) knockout mice develop late-onset cortical cataracts." (PMID 33500475, 2021). "The goals of future studies are to elucidate this S100A4 function on the mechanistic level and to understand how the absence of S100A4 induces late-onset cortical cataracts." (PMID 33500475, 2021).
crescentic glomerulonephritis (1 paper, 2017). A histopathologic term for a pattern of diseases characterized by extensive crescent formation in the glomeruli; patients present clinically with rapid deterioration of renal function, and possible progression to end-stage renal failure within weeks or months. "Urine S100A4 levels have previously been described to correlate with disease activity in various forms of crescentic glomerulonephritis." (PMID 29065913, 2017).
dermatomyositis (1 paper, 2014). Dermatomyositis (DM) is a type of idiopathic inflammatory myopathy characterized by evocative skin lesions and symmetrical proximal muscle weakness. "Serum levels of S100A4 were determined in 43 dermatomyositis (DM), 39 polymyositis (PM) and 22 cancer associated myositis (CAM) patients as well as in 77 healthy controls." (PMID 25359220, 2014).
ductal carcinomas (1 paper, 2019). "CYR61 and S100A4 are highly expressed in invasive-ductal carcinomas, including TNBC, and both are expressed in metastatic lymph node sections." (PMID 31709177, 2019).
emphysema (1 paper, 2015). "The established mouse model of smoke-induced emphysema was utilized to analyze the expression and specific localization of S100A4." (PMID 26483185, 2015). "Analogous to human lungs, in mice with tobacco-smoke-induced emphysema an up-regulation of S100A4 mRNA and protein was observed in intrapulmonary arteries." (PMID 26483185, 2015). "In addition to the experimental emphysema mouse model, we examined the localization and expression of S100A4 in patients suffering from COPD." (PMID 26483185, 2015).
end stage renal disease (1 paper, 2022). "Therefore, S100A4 may function as an alternative target for the prevention of chronic kidney disease." (PMID 36078170, 2022). "Manipulating S100A4 may provide a beneficial therapeutic strategy for chronic kidney disease." (PMID 36078170, 2022).
endocardial fibroelastosis (1 paper, 2023). Endomyocardial fibroelastosis is a cause of unexplained childhood cardiac insufficiency. "Specifically, 12 of 14 (86%) neonates with the most severe scores—advanced AV block and/or at least one extranodal manifestation—have the highest serum levels of S100A4 (>86 ng/mL); the lowest of the 14 being a milder case (endocardial fibroelastosis with no block)." (PMID 37090702, 2023).
ependymoma (1 paper, 2008). A WHO grade II, slow growing tumor of children and young adults, usually located intraventricularly. "In ependymoma we have shown that S100A4 is significantly associated with patients under the age of 3 years at diagnosis in intracranial paediatric ependymoma (P=0.038)." (PMID 18781180, 2008). "S100A4, was implicated in ependymoma as, again, being one of the most highly expressed genes in ependymoma with very low expression in ‘normal’ brain." (PMID 18781180, 2008). "S100A6 is significantly associated with paediatric ependymoma arising in the supratentorial compartment and S100A4 strongly correlates with patients aged less than 3 years at diagnosis." (PMID 18781180, 2008). "Of the 13 S100 genes, S100A4 had the highest mean tag count for ependymoma relative to normal brain with a fold change of 20.7 and S100A10 had the highest mean tag count of 133 in ependymoma." (PMID 18781180, 2008). "S100A4, a third member of the S100 family, was also one of the most upregulated genes in ependymoma with a difference in tag count of 6.6." (PMID 18781180, 2008). "Although S100A4 is one of the best characterised of the S100 genes in terms of its role in cancer, no other study has previously reported a link with patient age or explored its role in ependymoma." (PMID 18781180, 2008). "Protein expression levels of S100A10, S100A6, S100A4 and S100A2 were determined by immunohistochemistry using an independent cohort of seventy-four primary paediatric ependymoma arrayed on a tissue microarray." (PMID 18781180, 2008). "Candidates (CHI3L1, S100A10, S100A4, S100A6 and S100A2) were validated using immunohistochemistry on a tissue microarray of 74 paediatric ependymoma." (PMID 18781180, 2008). "S100A4 and S100A6 are clearly differentially expressed in paediatric ependymoma and can be used to distinguish clinically and biologically relevant subgroups." (PMID 18781180, 2008). "In conclusion, this study provides evidence that S100A6 and S100A4 are differentially expressed in clinically relevant subgroups, and also demonstrates a link between CHI3L1 protein expression and necrosis in intracranial paediatric ependymoma." (PMID 18781180, 2008). "The significance of S100A4 in ependymomas arising in children under 3 years of age is not clear but its differential expression demonstrates that there is a distinction between genetic events occurring in children of different ages." (PMID 18781180, 2008).
epididymitis (1 paper, 2025). Inflammation of the epididymis. "Recent studies have reported that S100a4 may promote the progression of LPS-induced epididymitis and contribute to reduced sperm vitality." (PMID 41031892, 2025).
epididymo-orchitis (1 paper, 2025). A disorder involving inflammation of the epididymis and testes. "Our data further reveal that these cells can adopt a myofibroblast state and directly contribute to the fibrotic process in UPEC-induced epididymo-orchitis in vivo, whereas therapeutic targeting of S100a4+ TM substantially reduced pathology." (PMID 41031892, 2025). "TLR4 has been previously characterized as a receptor mediating S100A4 signaling; our study reveals a distinct pathological mechanism underlying UPEC-induced epididymo-orchitis." (PMID 41031892, 2025). "Our findings establish the critical role of S100a4+ macrophages in fibrosis during UPEC-induced epididymo-orchitis and propose them as potential targets for antifibrotic therapy development." (PMID 41031892, 2025). "To do this, we treated mice with the S100a4 inhibitor niclosamide and observed the impact on fibrotic pathology in the UPEC-induced epididymo-orchitis model." (PMID 41031892, 2025).
Epiretinal membrane (1 paper, 2018). An epiretinal membrane is a thin sheet of fibrous tissue on the surface of the retina along the inner limiting membrane. "The relatively higher immunostaining of ET-1 and S100A4 in PDR epiretinal membranes may be an indication that PDR epiretinal membranes arise via different mechanisms than idiopathic epiretinal membranes." (PMID 29351334, 2018).
Fibroadenoma (1 paper, 2019). A benign tumor of the breast characterized by the presence of stromal and epithelial elements. "Moreover, we found more S100a4 expressing cells in the two malignant tumors compared to fibroadenoma (51–56% vs 26%)." (PMID 31881983, 2019).